PDPK1 (3-phosphoinositide dependent protein kinase 1)
Diseases named in the same sentence as PDPK1 in open-access papers (continued):
Sharing a sentence is not in itself a finding about the gene and the disease.
melanoma (12 papers, 2013 to 2025). A malignant, usually aggressive tumor composed of atypical, neoplastic melanocytes. "The loss of phosphoinositide-dependent kinase-1 (PDPK1) showed clinical relevance for the therapeutic efficacy of MEKis in melanoma, as demonstrated by clinical studies." (PMID 41369373, 2025). "However, the synergistic effect of PDPK1 depletion and MEKi was further investigated in melanoma cell lines with NRAS-mutation." (PMID 41369373, 2025). "It suggests that PDPK1 play a significant role in tumour-promoting performance in patients with NRAS mutant melanoma." (PMID 36551688, 2022). "Previous studies reported that PDPK1 was significantly upregulated in several human cancers, such as melanoma, multiple myeloma, head and neck carcinoma, and HCC 29-32." (PMID 32206125, 2020). "Previous researchers found that inhibiting PDPK1 expression in small cell lung cancer and melanoma can inhibit tumor progression." (PMID 33029112, 2020). "The clinical relevance of the combination of PDPK1 and MEK inhibitors was also demonstrated in the NRAS-mutated xenograft model, indicating the efficiency of the combinatorial strategy for the treatment of melanoma patients with NRAS mutation." (PMID 41369373, 2025). "In melanoma cells, the elevated genes included MAP2K7, RIOK1, GOPC, KHDC4 and PDPK1, which may be associated with stress/drug resistance, protein synthesis, and the regulation of cellular migration." (PMID 41383633, 2025). "Furthermore, PDPK1 is frequently amplified at the gene level or over-expressed in several tumour types, including melanoma." (PMID 29596374, 2018). "Therefore, the development of combination therapy for treating melanoma patients is justified by targeting PDPK1 to stimulate antitumor immunity and sensitise NRAS mutant melanoma to MEK inhibition." (PMID 36551688, 2022). "As the PDPK1-AKT pathway, in addition to activating the transcription of HIF-1α, also promotes cell surface expression of GLUT1, inhibition of AKT phosphorylation by ACF might have a major impact on glucose metabolism in melanoma cells." (PMID 33396270, 2020). "In addition to disturbing glucose metabolism in melanoma cells, the inhibition of the PI3K/PDPK1 pathway by ACF may also have important consequences for the pathobiology of these cells." (PMID 33396270, 2020).
pancreatic cancer (12 papers, 2013 to 2026). "Similar results were shown in pancreatic cancer cells, where miR-375 suppressed cell growth and induced apoptosis by negatively regulating the expression of 3-phosphoinositide-dependent protein kinase 1 (PDK1)." (PMID 37443682, 2023). "That PDPK1-governed CSC function can translate into enhanced tumor initiation in vivo has recently been elegantly shown in autochthonous pancreas cancer models." (PMID 34079928, 2021). "These observed associations of perturbations of PDPK1 expression patterns in patients’ specimens suggest that PDPK1 regulation might be involved in pancreatic carcinogenesis and pancreas cancer biology." (PMID 30064387, 2018). "Collectively, our findings reveal a novel mechanism of acetylcholine-induced enhancement of HIF-1α expression involving PDPK1/YAP signaling and highlight the utility of HIF-1α as a therapeutic target in acetylcholine-potentiated pancreatic cancer." (PMID 41608625, 2026). "PDPK1, one of the members of an upregulated EGF-signaling network in LRCC, mediates resistance to gemcitabine, is found to be dysregulated in pancreas cancer specimens, and might be an attractive molecular target for combination therapy studies." (PMID 30064387, 2018). "Of note, the combination of Bcl‐2/Bcl‐xL/Bcl‐W antagonists and drugs targeting PDPK1/Akt has thus far not been discussed as a treatment option for pancreatic cancer, further demonstrating the applicability of our model to identify innovative combinatorial approaches." (PMID 32073727, 2020).
glioblastoma (9 papers, 2020 to 2025). The most malignant astrocytic tumor (WHO grade IV). "In human glioblastoma cells, α-KG has been shown to enhance PDPK1 transcription by reducing the inhibitory histone modification H3K27me3, thereby promoting the activation of the PI3K/Akt/mTOR pathway." (PMID 41428315, 2025). "IL-6 secreted by in situ macrophages regulated the direction of a PGK1-catalyzed reaction by increasing PDPK1-dependent PGK1 phosphorylation in glioblastoma cells, promoting glycolysis and proliferation of tumor cells." (PMID 35600367, 2022). "In addition, PGK1 T243 phosphorylation correlates with PDPK1 activation, IL-6 expression, and macrophage infiltration in human glioblastoma (GBM) and correlates with the malignancy and prognosis of human GBM." (PMID 37491279, 2023).
gastric cancer (6 papers, 2017 to 2023). A primary or metastatic malignant neoplasm involving the stomach. "A recent report showed that circRNA-0000081 maintains the levels of PDPK1 (a target of miR-423) in gastric cancer cells via miR-423 sponging, thereby affecting cell proliferation, migration, and invasion potential." (PMID 38053184, 2023). "Previous studies have demonstrated that PDPK1 activated the NK-κB signaling pathway in human gastric cancer." (PMID 33384993, 2020).
hepatocellular carcinoma (5 papers, 2020 to 2023). A malignant tumor that arises from hepatocytes. "Increased PDPK1 expression promotes gemcitabine resistance in pancreatic adenocarcinoma cells and radiation resistance in hepatocellular carcinoma." (PMID 38028209, 2023).
multiple myeloma (5 papers, 2013 to 2022). "Interestingly, combined RNAi screens (Broad Institute, Novartis and Marcotte), demonstrate that multiple myeloma shows a high dependency on the PDPK1 gene, which encodes PDK1." (PMID 32228485, 2020). "In myeloma cells, PDPK1 is overexpressed mainly by the epigenetic repression of miR-375, maintaining its constitutively active status through autophosphorylation." (PMID 35328342, 2022). "We previously demonstrated that PDPK1, the master kinase of series of AGC kinases, is universally active in MM, and plays pivotal roles in cell proliferation and cell survival of myeloma cells regardless of the profiles of cytogenetic and genetic abnormalities." (PMID 35328342, 2022).
ovarian carcinoma (5 papers, 2017 to 2024). A malignant neoplasm originating from the surface ovarian epithelium. "In this research, we found that a high expression of PDPK1 was associated with poor prognosis in patients with ovarian cancer." (PMID 39624293, 2024). "Further, the high PDPK1 expression level was closely related to the poor prognosis of patients with ovarian cancer." (PMID 39624293, 2024). "Of note, the pharmacological inhibition of PDPK1 has been found to increase the effect of chemotherapy drugs on ovarian cancer." (PMID 39624293, 2024). "Recent studies have shown that PDPK1 is involved in the invasiveness of ovarian cancer via short Ron receptor tyrosine kinase and COL11A1." (PMID 39624293, 2024). "Moreover, combined with bioinformatics analyses, we found that the high expression of PDPK1 is closely related to the poor prognosis of patients with ovarian cancer, which implies that PDPK1 can impact the development of ovarian cancer." (PMID 39624293, 2024). "We found a correlation between high PDPK1 expression and worse prognosis of ovarian cancer patients, which suggested that PDPK1 may play an oncogenic role in EOC." (PMID 39624293, 2024). "Recently, PDPK1 has been reported to be closely related to the invasion of ovarian cancer." (PMID 39624293, 2024).
colorectal cancer (4 papers, 2020 to 2023). A primary or metastatic malignant neoplasm that affects the colon or rectum. "Further, they can inhibit the growth of colorectal cancer cells in vivo and in vitro by inducing apoptosis through the 3-phosphoinositide-dependent protein kinase-1 (PDK1)/AKT/Bcl-2 signaling pathway." (PMID 36613399, 2023). "The combination of small molecules including imatinib targeted MCL1 and celecoxib targeted PDPK1 was reported to treat the HT30 colorectal cancer." (PMID 32523951, 2020).
glioma (3 papers, 2020 to 2023). A benign or malignant brain and spinal cord tumor that arises from glial cells (astrocytes, oligodendrocytes, ependymal cells). "IL-6 secreted by M2 macrophages promoted glycolysis of GBM cells by phosphorylating PGK1 via 3-phosphoinositide-dependent protein kinase 1 (PDPK1), and quinolinic acid secreted by microglia was taken up by glioma cells for the synthesis of NAD+ to resist oxidative stress." (PMID 34211978, 2021).
Hyperglycemia (3 papers, 2015 to 2019). An increased concentration of glucose in the blood. "Loss of PDPK1 in β cells results in progressive hyperglycemia due to reductions in the number and size of β cells, as well as defective β cell function." (PMID 28264477, 2017). "Indeed, mice deficient in PDPK1 in β cells manifest reduced β-cell numbers and hyperglycemia, while AKT overexpression under the Pdx1 promoter results in β-cell dedifferentiation." (PMID 25875172, 2015). "We then established transgenic flies, where CncC/Nrf2 OE was combined with InR or Pdpk1 KD and found that both genetic interventions largely rescued the CncC/Nrf2 OE‐mediated larval growth retardation and mitigated CncC/Nrf2 OE‐induced hyperglycemia in adult flies." (PMID 30537423, 2019).
Insulin resistance (3 papers, 2016 to 2018). Increased resistance towards insulin, that is, diminished effectiveness of insulin in reducing blood glucose levels. "Similarly, inhibition of Pdpk1 by celecoxib might cause increase in insulin resistance through inhibition of Ins." (PMID 28731442, 2017). "Our data suggest that PT has the potential to regulate insulin resistance and metabolic syndrome by lowering the mRNA expression of PDPK-1, CCR4, CCR6, and CCL4L2 in PBMCs." (PMID 27869712, 2016). "Pdpk1 also inhibits Ccr2, M1 macrophages, and insulin resistance." (PMID 28731442, 2017). "On the other hand, mice lacking 3-phosphoinositide-dependent protein kinase 1 (PDK1) in the myeloid cells, which are downstream signaling molecules in the IR/Irs2 pathway, showed adipose tissue inflammation and insulin resistance under the HF diet condition." (PMID 30451856, 2018).
nasopharyngeal carcinoma (3 papers, 2014 to 2022). A carcinoma arising from the nasopharyngeal epithelium. "miR-138 inhibited cancer cell growth and tumorigenesis in non-small cell lung cancer and nasopharyngeal cancer by targeting 3-phosphoinositide-dependent protein kinase-1 (PDK1) and CCND1." (PMID 24941171, 2014). "Experiments with hLf demonstrated the further downregulation of 3-phosphoinositide-dependent protein kinase 1 (PDK1) transcription via mitogen-activated protein kinase/c-Jun pathway following deactivation of AKT signaling leading to inhibition of nasopharyngeal carcinoma (NPC) tumorigenesis." (PMID 34201342, 2021). "Neoalbaconol, a terpenoid isolated from the fungus Albatrellus confluens, targets PDPK1/PDK1 (3-phosphoinositide-dependent protein kinase 1) and inhibits the subsequent PI3K-AKT signaling in the nasopharyngeal carcinoma (NPC) nude mouse model, resulting in activation of autophagy." (PMID 36497321, 2022).
atherosclerosis (2 papers, 2020 to 2025). A disease characterized by the build-up of fatty material and calcium deposition in the arterial wall resulting in partial or complete occlusion of the arterial lumen. "The 6 ingredients were highly related to arteriosclerotic cardiovascular disease and atherosclerosis and could mainly interact with similar targets, e.g., GSK3B, PDPK1, PLAU, etc., or pathways, e.g., Insulin, VEGF, FoxO, etc, providing the basis for integrating plasma drug concentration." (PMID 32922299, 2020).
diabetes (2 papers, 2019 to 2025). "Finally, six genes (Sec61a1, Insr, Sirt1, Pdpk1, Sin3a, and Sqstm1) were predicted to be associated with diabetes and obesity." (PMID 32257911, 2019).
osteosarcoma (2 papers, 2023 to 2025). A usually aggressive malignant bone-forming mesenchymal neoplasm, predominantly affecting adolescents and young adults. "The study explores the prognostic significance and therapeutic potential of 3-phosphoinositide dependent protein kinase-1 (PDK1) in osteosarcoma." (PMID 40971960, 2025).
viral infection (2 papers, 2020 to 2022). "Therefore, gga-miR-148a-5p is a potential interfering target, which can promote the expression of PDPK1 to inhibit cell proliferation and improve the host's immunity to virus infection and tumor formation." (PMID 33384993, 2020). "Notably, CIMSS inhibited PDPK1, Akt, and PLCγ phosphorylation and reduced HSV entry and infection, highlighting the importance of extracellular kinase function/phosphorylation events in viral infection." (PMID 36245045, 2022). "No phosphorylated PDPK1 or PLCγ signal was detected in cells prior to HSV exposure, but both phosphorylated proteins were detected in images obtained 15 and 30 min following viral infection and their phosphorylation was inhibited by CIMSS." (PMID 36245045, 2022).
alcoholic hepatitis (1 paper, 2022). Acute hepatitis resulting from ingestion of alcohol. "Both inhibiting PDPK1 and the phosphorylation of PDPK1 (ser241) could protect hepatocytes from suffering heavy alcoholic hepatitis." (PMID 36418288, 2022).
allergic asthma (1 paper, 2015). A asthma with a basis in a pathological type I hypersensitivity reaction. "Furthermore, the upregulated genes (PDPK1, EZR, MYO6, CDC42BPA, OPHN1, ARF6 and WASL) identified in the present study that were enriched in the actin filament-based process require further study in order to determine whether they may be used as potential biomarkers of allergic asthma." (PMID 25633562, 2015).
Arrhythmia (1 paper, 2015). Any cardiac rhythm other than the normal sinus rhythm. "3-phosphoinositide-dependent protein kinase-1 (PDK1) is involved in the pathogenesis of arrhythmia, and its downstream factor, Forkhead box O1 (Foxo1), negatively regulates the expression of the cardiac sodium channel, Nav1.5." (PMID 25781322, 2015).
autoimmune disease (1 paper, 2022). A disorder resulting from loss of function or tissue destruction of an organ or multiple organs, arising from humoral or cellular immune responses of the individual to their own tissue constituents. "Since CD4 T-cell-specific PDPK1 deletion induces lymphoid atrophy, and PDPK1 deficiency in Treg cells generates severe spontaneous autoimmune diseases, which resemble the phenotypes observed in our KO and Treg-KO mice, we then examined PDPK1 and its downstream signaling molecules." (PMID 35210408, 2022).
B Cell lymphoma (1 paper, 2021). "We found that PDPK1 (also known as PDK1) was downregulated after POU2F2 knockdown in B Cell lymphoma cells, that could interact with AKT and phosphorylated it at T308." (PMID 33931589, 2021).
bladder cancer (1 paper, 2017). "The ceRNAs of PDPK1 in K13M4 might be potential biomarkers for bladder cancer." (PMID 29340088, 2017).
brain tumors (1 paper, 2021). "Knockdown of POU2F2 significantly suppressed the growth of brain tumors and increased the survival time of mice, and these effects were reversed by the recovered expression of PDPK1." (PMID 33931589, 2021).
breast tumors (1 paper, 2019). "We could show that corresponding CTCs resemble those of primary breast tumors, but identified alterations also in pathways known to be important in brain metastasis formation including notch (gain of NOTCH3) and PI3K (gain of PDPK1) pathways." (PMID 31481116, 2019).
cervical cancer (1 paper, 2020). A primary or metastatic malignant neoplasm involving the cervix. "Our study shows that the CAR10/miR-125b-5p/PDPK1 network plays an important role in the development of cervical cancer." (PMID 32025520, 2020). "Our study demonstrates that, based on ceRNA mechanism, CAR10/miR-125b-5p/PDPK1 network can regulate the proliferation of cervical cancer cells and play an important role in the development of cervical cancer." (PMID 32025520, 2020). "RT-qPCR results showed that the expression level of PDPK1 in cervical cancer tissues was significantly reduced." (PMID 32025520, 2020). "In cervical cancer cells, CAR10 acts as a ceRNA, which upregulates the expression of PDPK1 by sponging miR-125b-5p, thereby promoting the proliferation of cervical cancer cells." (PMID 32025520, 2020). "Can the CAR10/miR-125b-5p/PDPK1 network regulate the proliferation of cervical cancer cells?" (PMID 32025520, 2020). "In addition, in cervical cancer cells, overexpression of miR-125b-5p, or knockdown of PDPK1, can reverse the promotion of CAR10 on cervical cancer cell proliferation." (PMID 32025520, 2020). "In addition, we also confirmed that intervention of the CAR10/miR-125b-5p/PDPK1 network can inhibit the development of cervical cancer and provide a new strategy for targeted therapy of cervical cancer." (PMID 32025520, 2020). "Knockdown of PDPK1 can inhibit the effect of CAR10 on cervical cancer cells." (PMID 32025520, 2020). "Furthermore, the results of transwell assay showed that anti-miR-125b-5p can significantly enhance the migration of C33A and HeLa cells, while si-PDPK1 can reverse the effect of anti-miR-125b-5p on migration of cervical cancer cells." (PMID 32025520, 2020). "Does the CAR10/miR-125b-5p/PDPK1 network participate in the development of cervical cancer?" (PMID 32025520, 2020). "Further studies reveal that CAR10 can promote the expression of PDPK1 by sponging miR-125b-5p, which may be one of the mechanisms that promote the proliferation of cervical cancer cells." (PMID 32025520, 2020). "In addition, our study also suggests that intervention of CAR10/miR-125b-5p/PDPK1 network may be a new strategy for targeted therapy of cervical cancer." (PMID 32025520, 2020).
colon cancer (1 paper, 2018). "Celecoxib was used in colon cancer stem cell related treatment by targeting on PDPK1." (PMID 29723215, 2018).
congenital heart disease (1 paper, 2019). A heart disease that is present at birth. "Among these genes, AKT1, PDPK1, CDC42, AKT3, and PIK3CA have concrete evidences shown in relation with congenital heart disease; even two of them (AKT1, CDC42) have explicit association with VSD." (PMID 31440271, 2019).
Huntington disease (1 paper, 2016). Huntington disease (HD) is a rare neurodegenerative disorder of the central nervous system characterized by unwanted choreatic movements, behavioral and psychiatric disturbances and dementia. "It was interesting to note that genes involved in Huntington’s disease were enriched in this signature, namely MAP2K7, PDPK1, NCOR2, EP300, and REST." (PMID 27698411, 2016).
Infertility (1 paper, 2020). "Another protein kinase, 3-phosphoinositide-dependent protein kinase-1 (PDK1), is crucial for primordial follicle survival in mice, where PDK1 knockout oocytes cause infertility and premature ovarian aging." (PMID 32047242, 2020).
leukemia disease (1 paper, 2020). "In order to explore the function of PDPK1 in chicken leukemia disease, we detected NK-κB activity in ALV-J-infected CEF cells after si-PDPK1 transfection using a NF-κB luc plasmid." (PMID 33384993, 2020).
lung adenocarcinoma (1 paper, 2021). A carcinoma that arises from the lung and is characterized by the presence of malignant glandular epithelial cells. "As the terminal of the ceRNA axis that we discovered, the downstream signaling pathway regulated by PDPK1 and the mechanism of its influence on the malignant progression of lung adenocarcinoma remain to be clarified." (PMID 34992655, 2021).